EGF (epidermal growth factor)
Diseases named in the same sentence as EGF in open-access papers (continued):
Sharing a sentence is not in itself a finding about the gene and the disease.
glioma (continued). "Previous studies showed that the EGF +61G/A polymorphism (rs4444903) may lead to an alteration in EGF production and/or activity, which can result in individual susceptibility to glioma." (PMID 22829952, 2012). "Hence, a meta-analysis of seven case-control studies involving 1,613 cases and 2,267 was performed to derive a more precise estimation of the association of EGF +61G/A with glioma risk." (PMID 22829952, 2012). "However, in the stratified analysis by ethnicity, the EGF +61G/A polymorphism had a higher risk of glioma development among Asians, but a lower risk among Caucasians." (PMID 22829952, 2012). "The number of patients in most of former studies about the association of EGF +61 G/A to cancers were less than 300, which might lead to a different result from our study involving 677 glioma patients and 698 healthy controls." (PMID 20487573, 2010). "The role of EGF +61 A/G polymorphism in glioma susceptibility needs further investigation." (PMID 20487573, 2010). "Therefore, it is logical to hypothesize that functional genetic polymorphisms involving EGF or EGFR may predispose to glioma development." (PMID 24740103, 2014). "Secondly, the association between EGF +61A/G and glioma risk was controversial in our study and Caucasions, Thus, studies with ethnically diverse populations are warranted to confirm our findings and to further elucidate the significance of the polymorphism in the development of gliomas." (PMID 20487573, 2010). "Pathway communication analysis by CellChat revealed S100A9 Ma’s interactions with other cell types, engaging in the EGF pathway with glioma cells and the VEGF pathway with endothelial cells." (PMID 39136841, 2024). "Our data collectively describe the Fyn-YANK2-p70S6K signaling axis, which regulates cell growth activity, tumorigenicity and response to EGF in glioma." (PMID 38714727, 2024). "Other studies have also demonstrated that TAM-derived factors such as VEGF, EGF, bFGF, IL-1β and IL-6 are able to facilitate glioma vascularization." (PMID 37705736, 2023). "Chemoattractants such as MCP-1 (CCL2), MCP-3 (CCL7), SDF-1 (CXCL12), CX3CL1, POSTN, GM-CSF, M-CSF (CSF-1) and EGF produced by glioma cells actively recruit TAMs and thus promote tumor growth." (PMID 37705736, 2023). "Other factors that promote glioma progression and invasiveness include epidermal growth factor (EGF) expression, stress-inducible protein 1 (STI1) expression and Toll-like receptor 2 (TLR2) upregulation." (PMID 38275375, 2023). "Variations in genes involved in DNA repair, cell cycle, metabolism, and inflammation pathways have been recognized as a key basis of inherited glioma susceptibility, such as PRKDC, XRCC1, PARP1, ERCC1, ERCC2, EGF, and IL13." (PMID 36733406, 2023). "Glioma cell-derived EVs taken up by astrocytes increase their migratory capacity and activate oncogenic signaling pathways such as epidermal growth factor (EGF) and mitogen-activated protein kinase (MAPK)." (PMID 38275375, 2023). "Reduced P2RX7 expression resulted in the development of various cancers and P2RX7 inhibition by shRNA in glioma tissue increased EGF and phosphor-EGF protein expression." (PMID 36741002, 2023). "The formation of neurospheres from monolayer (MN) cultures of glioma cells is carried out under conditions of cell cultivation in a serum-free medium in the presence of epidermal growth factor (EGF) and basic fibroblast growth factor (bFGF)." (PMID 36354672, 2022). "TRPC1 activation in response to EGF-induced chemotaxis regulates Cl− channel activity in glioma cells in a calcium-dependent manner." (PMID 36497413, 2022). "The [111In-DTPA, PEG3400-biotinyl]-EGF/SA-OX26 was injected intravenously in nude rats bearing an intracranial human U87 glioma, which over-expresses the EGFR." (PMID 35745855, 2022). "These cell lines are enriched for glioma stem cells and are grown in the presence of the growth factors EGF and FGF224." (PMID 35149717, 2022).
glioma (continued). "The use of a targeted EGF peptide radiopharmaceutical as an imaging agent in experimental brain cancer was evaluated with an experimental intra-cranial U87 human glioma in nude rats." (PMID 35745855, 2022). "In glioma cells, the epidermal growth factor (EGF)/EGFR signaling through ERK1/2 leads to the phosphorylation of α-catenin, which, together with cadherin, forms a complex linked to the cytoskeleton, promoting β-catenin transactivation and glioma cell invasion." (PMID 35303162, 2022). "We also detected that the upregulation of SPRY4, ERRFI1 and RAB31 provides a condition for feedback regulations of FGF and EGF signaling as well as can be applied in glioma therapy." (PMID 36231068, 2022). "One of the most commonly used components for neurosphere formation are EGF and bFGF; they allow the generation of spheres that are much more similar to human glioblastoma than to tumors initiated by glioma cell lines." (PMID 36231068, 2022). "Taking into account the strong autocrine expression of SDF-1α in CL2, we can state that SDF-1α in the glioma environment, together with EGF and PDGFβ, are the main regulators of glioma cell dispersal." (PMID 34944779, 2021). "A possible explanation of this effect is the extremely high autocrine gene expression of SDF-1α, IL-8, and EGF by CL1 glioma cells and, consequently, a high basal level of Pyk2 expression and phosphorylation in this cell line." (PMID 34944779, 2021). "In contrast to PDGFα, PDGFβ, and SDF-1α, whose functions appear to be patient-specific, EGF and IL-6 are implicated in Pyk2- and FAK-mediated glioma cell proliferation in all subjects evaluated." (PMID 34944779, 2021). "For instance, thalidomide is being tested in glioma and it has been shown to inhibit EGF-induced phosphorylation of extracellular signal regulated kinase (ERK), as well as EGF-induced Ras activation by preventing transition to GTP-bound active Ras." (PMID 35096619, 2021). "In glioma, S100A4 expression is affected by DNA methylation, β-linked proteins, and extracellular factors including epidermal growth factor and tumor necrosis factor alpha (TNF-α)." (PMID 34148033, 2021). "When cultured under serum-free conditions supplemented with epidermal growth factor (EGF) and basic fibroblast growth factor (bFGF), GSCs can self-renew to produce spheres called "glioma neurospheres"." (PMID 34635112, 2021). "The strong positive correlation between the Pyk2 and FAK protein levels in glioma and mRNA levels of EGF, PDGFβ, SDF-1α, and IL-8 is supported by the upregulation of phosphorylated Pyk2 and FAK following treatment with cytokines and chemokines." (PMID 34944779, 2021). "Our results expand on those of previous studies indicating that the activation of Pyk2 and FAK in gliomas is induced by microglia-derived EGF, PDGFβ, SDF-1α, IL-6, and IL-8." (PMID 34944779, 2021). "In Normal Medium, cells are spread out in the petri dish, whereas in Define Medium, cells develop the ability to form glioma spheres due to the presence of specific growth factors (EGF and bFGF-2)." (PMID 34677344, 2021). "Microglia treated with glioma-conditioned medium (GCM) from primary cell lines increased the expression of genes encoding PDGFβ, SDF-1α, IL-6, IL-8, and EGF." (PMID 34944779, 2021). "Recently, the Fine group reported that tumors generated by cells from glioblastoma multiforme (GBM) spheres grown in EGF and bFGF were much more similar to the human glioblastoma than tumors initiated by glioma cell lines." (PMID 32102678, 2020). "We propose that a standard glioma stem cell culture media should include neurobasal medium with N2 (Gibco), EGF, bFGF, leukemia inhibitory factor, and heparin to avoid inconsistencies in glioma stem cell research due to technical culture issues." (PMID 32102678, 2020). "EGF can keep EGF-responsive glioma stem cells in suspension and bFGF can promote the long-term growth of glioma stem cells." (PMID 32102678, 2020).
glioma (continued). "Glioma stem cells cultured in epidermal growth factor (EGF) and basic fibroblast growth factor (bFGF) have been reported to more closely mirror the phenotype and genotype of primary tumors than serum-cultured cell lines." (PMID 32102678, 2020). "Recently, EGF and bFGF have been used in glioma stem cell culture as well as for neural stem cell culture." (PMID 32102678, 2020). "The concentrations of growth factors, especially EGF and bFGF, being used in the glioma stem cell media varied considerably among the published groups." (PMID 32102678, 2020). "In malignant gliomas, WTAP can regulate migration and invasion through EGF signaling, and closely related to glioma severity and postoperative survival rate of glioma patients." (PMID 33552994, 2020). "A study has shown that the binding of EGF to EGFR in human glioma cells induces tyrosine kinase-dependent Ca2+ oscillations." (PMID 32841278, 2020). "Acute human glioma cell stimulation with EGF evokes intracellular Ca2+ responses as oscillations, which are blocked by EGFR inhibitors." (PMID 32841278, 2020). "Considering that different IDH-dependent glioma subtypes have different EGF activation status, it is reasonable to identify such gene and its targeted probe as one of the potential markers for such IDH-dependent subtyping." (PMID 31803734, 2019). "As for the methylation status and expression pattern of such gene in different glioma subtypes, it has been identified as one of the potential markers reflecting the activation status of EGF signaling pathway." (PMID 31803734, 2019). "Abrogating 6PGD Y481 phosphorylation (pY481) dramatically attenuates EGF-promoted glioma cell proliferation, tumor growth and resistance to ionizing radiation." (PMID 30824700, 2019). "On the other hand, a role for TRPC1 in glioma cell chemotaxis induced by epidermal growth factor (EGF) has been demonstrated." (PMID 31801263, 2019). "First, infiltrating tumor-associated macrophages (TAM) release several factors such as TGFβ, stress-inducible protein 1 (STI1), epidermal growth factor (EGF), IL-6 and IL-1β to promote glioma cell invasion." (PMID 31225500, 2019). "Epidermal growth factor (EGF) and colony-stimulating factor-1 (CSF-1) have also been implicated in TAM glioma crosstalk." (PMID 31231208, 2019). "The outcomes indicated that CED was more effective than intratumoural injection to deliver boronated EGF to EGFR(+) gliomas for boron neutron capture therapy." (PMID 31783573, 2019). "Glioma-associated macrophages express and secrete multiple factors including STI1, EGF (epidermal growth factor), TGF-β, and MT1-MMP to promote glioma cell survival, proliferation, and migration." (PMID 29422647, 2018). "M1 and M2 types of microglia were shown to promote glioma cell invasion by exchanging signaling molecules such as CSF-1, EGF and TGF-β." (PMID 30286133, 2018). "Meanwhile, several GAM-derived factors such as TGF-β, stress-inducible protein (STI)-1, IL-6, IL-1β, and EGF have been identified as promoters of glioma cell invasion." (PMID 29389898, 2018). "In present study, we found that BTK inhibition can significantly block the degradation of IκBα and prevent the nuclear accumulation of NF-κB p65 subunit induced by EGF in glioma cells." (PMID 28946903, 2017). "Meanwhile, EGR1 overexpression induced by EGF was able to promote the proliferation of glioma cells." (PMID 29246166, 2017). "More importantly, we found that BTK inhibition significantly blocks the degradation of IκBα and prevents the nuclear accumulation of NF-κB p65 subunit induced by EGF in glioma cells." (PMID 28946903, 2017). "Regression and pathway analysis implicated IL8, PTEN, PI3K/Akt, Neuregulin, ERK/MAPK, p70S6K and EGF signaling pathways, mechanisms that exert control over the cell cycle, growth, and proliferation and are known to be significantly altered in gliomas." (PMID 28781988, 2017). "In glioma cells treated with EGF, overexpression of miR-338 reduced the binding between β-catenin and PKM2." (PMID 28858851, 2017).
glioma (continued). "In our literature search, we also found two papers that cultured primary glioma cells in media supplemented with a mixture of EGF, FGF-2 and PDGF." (PMID 28978189, 2017). "A lower percentage of EGF-treated glioma cells were observed to be in S phase after transfection with miR-338 than after transfection with miR-Scr." (PMID 28858851, 2017). "To further clarify the SCD1-mediated Akt signaling axis in TMZ-resistant glioma cells, we used the Akt activator, EGF, to activate Akt signaling, and the Akt direct inhibitor (MK2206) and indirect inhibitor (LY294002) to inactivate Akt signaling." (PMID 29354058, 2017). "For example, in vitro and in situ studies suggested that blocking migration of C6 glioma cells by directly targeting myosin II with blebbistatin was very effective even in the presence of several effective signaling pathways such as EGF and PDGF." (PMID 28166231, 2017). "EGF or PDGF can induce the synthesis of EGR1 via ERK signal pathway in human glioma cells, suggesting that EGR1 functions as a “third messenger” in glioma cells." (PMID 29246166, 2017). "This was consistent with previous reports, which showed that EGF signaling increased the EGR1 mRNA concentration in human glioma cells within 30 min." (PMID 29246166, 2017). "Meanwhile, it blocked glioma cell migration by oligomeric hyaluronan or epidermal growth factor (EGF)." (PMID 28399876, 2017). "Wnt-independent mechanisms of beta-catenin activation also exist in glioma including the EGF/EGFR pathway." (PMID 27613837, 2016). "High level expression of PDGF and EGF in TAMs supports tumour cell growth and triggers angiogenesis in the glioma environment." (PMID 27385209, 2016). "Signaling pathways coupled to DAG generation are highly active in glioma, mainly downstream of activated epidermal growth factor (EGF) and platelet-derived growth factor (PDGF) receptors." (PMID 25682201, 2015). "The cholesterol-lowering medication simvastatin also enhances CD44 shedding; it also blocks the stimulation of glioma cell migration by oligomeric hyaluronan or EGF." (PMID 26347743, 2015). "A prominent abnormality of certain malignant tumor cells, e.g., gliomas, is overexpression of the EGF receptor, and EGF induces CD44 shedding, that concomitantly enhance hyaluronan-mediated cell migration." (PMID 26347743, 2015). "In contrast, CD9 knockdown enhanced both basal and EGF-induced invasion of glioma cells, consistent with its anti-invasive role as shown in prior studies." (PMID 26377974, 2015). "To gain further insight into the regulation of signaling pathways in V12-Ras-astrocytes derived from 12 V-Ha-Ras transgenic mice, we stimulated the glioma cells derived from these transgenic mice with EGF." (PMID 25425962, 2014). "We demonstrate that treatment of SF1126 decreased the baseline and EGF-stimulated levels of phospho-ERK in glioma cells derived from 12 V-Ha-Ras transgenic mice." (PMID 25425962, 2014). "U87 glioma cells were first infected with lenti-AS-566 and then EGF was introduced to activate EGFR signaling." (PMID 24650032, 2014). "In this report, we provided evidences that GSK-3 was important for serum- or EGF-stimulated glioma cell invasion." (PMID 24312592, 2013). "STAT3 activation in glioma TAMs is induced by many mediators known to compose the local tumor microenvironment such as IL-10, IL-6, EGF, and FGF." (PMID 23737783, 2013). "Taken together, these results suggested that GSK-3α and -3β were important for EGF-induced glioma cell invasion, in which GSK-3β was specifically regulated in an asymmetric way." (PMID 24312592, 2013). "On the other hand TRP and ORAI1 channels functionally interact with other family of channels: a nice example is TRPC1 which is functionally related to ClC-3 in caveolar lipid rafts of glioma cells to promote EGF-induced chemotaxis." (PMID 24204345, 2013). "Our work provided supportive evidences that GSK-3 played a critical role of in glioma cell invasion, especially in EGF-stimulated migration." (PMID 24312592, 2013).
glioma (continued). "Although both GSK-3α and 3β activities were regulated by serum and EGF, they likely played different roles in glioma cell migration." (PMID 24312592, 2013). "In two separate efforts, activated microglia from a murine glioma model demonstrated expression of EGFR as well as low levels of EGF secretion." (PMID 23737783, 2013). "Here, we reported that GSK-3β was involved in the formation of cell polarity to affect glioma cell invasion, and it was also important for EGF-stimulated glioma cell invasion." (PMID 24312592, 2013). "These initial findings again position TAMs within a potential paracrine network with glioma cells, acting to reinforce expression of both EGF and EGFR on glioma cells to promote tumor progression." (PMID 23737783, 2013). "GSCs are characterized by the ability of self-renewal to generate spheres termed "neurospheres" or "glioma neurospheres" when cultured in serum-free conditions supplemented with epidermal growth factor (EGF) and basic fibroblast growth factor (bFGF)." (PMID 22330721, 2012). "After stimulating glioma cells with EGF, NKCC1 phosphorylation increased in a time-dependent and dose-dependent manner in NS318 and NS567 cells." (PMID 22570591, 2012). "EGF-SubA was well tolerated in mice and led to a significant tumor growth delay in a glioma xenograft mouse model." (PMID 23284962, 2012). "Based on the clear biologic relevance the UPR and GRP78 play in glioma tumorigenesis, we explored the anti-tumor potential of EGF-SubA in glioblastoma models." (PMID 23284962, 2012). "Epidermal growth factor receptor (EGFR), an important receptor of EGF with high affinity, was often overexpressed in glioma cells." (PMID 22829952, 2012). "In the presence of EGF stimulus, Bmi-1 localizes in chromatin of glioma stem cells (GSCs), evidenced by the fact that Bmi-1 in GSCs co-localizes with histone H3 in the immunocytochemistry image (data not shown)." (PMID 21305053, 2011). "We therefore enriched immature glioma cells by culturing single cell suspensions of freshly resected glioblastomas in serum-free medium supplemented with EGF and FGF-2 to favor the growth of undifferentiated cells." (PMID 21663643, 2011). "An EGF-SubA fusion protein has recently been shown to kill EGFR-positive rat glioma and human breast and prostate cancer cells at picomolar concentrations." (PMID 20871837, 2010). "Living glioma and normal cells or tissue biopsies were incubated with QDs coupled to EGF and/or monoclonal antibodies against EGFR for 30 minutes, washed and imaged." (PMID 20614029, 2010). "Epidermal growth factor receptor (EGFR) is a 170 kDa transmembrane tyrosine kinase that binds to EGF and mediates signalling pathways leading to survival, proliferation, migration and invasion of glioma cells." (PMID 19018263, 2008). "But in vitro culture of glioma cells in NBM+B27 with EGF+bFGF promotes gliosphere formation in 5–7 days that increase in size by 7–10 days (b1, f1)." (PMID 19018263, 2008). "Complex interactions of functional TGF-β and EGF signal cascades in human gliomas have also been described." (PMID 17453002, 2007). "EGFR activation increased nuclear FABP7 immunoreactivity in a glioma cell line in vitro, and inhibition of FABP7 expression suppressed EGF-induced glioma-cell migration." (PMID 16623952, 2006). "Similarly, EGF stimulated EGFR in glioma cells which subsequently phosphorylated the carboxy terminal of the GluN2B subunit of NMDAR and enhanced glutamate-NMDAR signaling and then glioma cell migration." (PMID 40405084, 2025). "Earlier efforts of neurosphere generation date back to the early 1990s, and in the early 2000s, several studies demonstrated the successful generation of neurospheres from putative glioma stem cells (GSCs) cultured with neurotrophic growth factors like epidermal growth factor (EGF) and FGF2." (PMID 38003507, 2023).